FGF19 (fibroblast growth factor 19)
Diseases named in the same sentence as FGF19 in open-access papers (continued):
Sharing a sentence is not in itself a finding about the gene and the disease.
morbid obesity (2 papers, 2019 to 2023). An excess of body weight, normally defined as an individual with a body mass index greater than 35 or a body weight greater than one hundred percent of ideal body weight. "A randomized controlled study in patients with morbid obesity showed that UDCA administration stimulated BA synthesis by reducing circulating fibroblast growth factor 19 and farnesoid X receptor activation." (PMID 36881180, 2023). "Although increased FGF 19 levels have been observed in patients with morbid obesity but without DM at 12 months after sleeve gastrectomy (SG), information regarding bile acids, FGF 19 and NAFLD dynamics in patients with T2DM after bariatric surgery is essential, but remains completely lacking." (PMID 31181641, 2019).
Oral cancer (2 papers, 2021 to 2025). "Our results showed that FGF19/FGFR4 were involved in the melatonin modulated oral cancer migration and invasion." (PMID 34576070, 2021). "Oral cancer overexpression 1 (ORAOV1) is located within the chromosome band 11q13, between cyclin D1 (CCND1) and fibroblast growth factor 19 (FGF19)." (PMID 41321947, 2025).
Osteopenia (2 papers, 2020 to 2022). Osteopenia is a term to define bone density that is not normal but also not as low as osteoporosis. "In summary, this cross-sectional study has found that the levels of serum bile acid and FGF19 were significantly lower in women with postmenopausal osteoporosis and osteopenia than in healthy women." (PMID 32187280, 2020). "This cross-sectional study found that serum bile acid and FGF19 levels were significantly lower in PMO and osteopenia than in healthy women." (PMID 35574015, 2022).
pancreatic cancer (2 papers, 2018 to 2025). "Next, the association between FGF19, FGF21, FGFR1, FGFR4, and KLB overexpression and the overall survival of pancreatic cancer patients was evaluated." (PMID 30593273, 2018). "For example, in models of pancreatic cancer, we discovered that HMGA1 activates pathways downstream of the fibroblast growth factor, FGF19, and inhibitors of FGF19 and its receptor (FGFR4) are already available in the clinic." (PMID 40076747, 2025).
tongue tumor (2 papers, 2017 to 2021). "Crucially, loss of FGF19 attenuated metastatic potential of tongue tumors that were derived from MT-LE HN30 cells." (PMID 33691750, 2021). "The therapeutic efficacy of FGF19/FGFR4 inhibition in melatonin-mediated tumor growth and metastasis was evaluated in orthotopic tongue tumor mice." (PMID 33691750, 2021).
Acute hepatitis (1 paper, 2024). Acute hepatic injury resulting from inflammation typically accompanied by increased serum alanine transaminase activity. "This hypothesis is also illustrated in our case by the detection of FGF23 mRNA alongside that of FGF19, the increased expression of which during acute hepatitis is already well established." (PMID 39525686, 2024).
acute pancreatitis (1 paper, 2014). An acute inflammatory process that leads to necrosis of the pancreatic parenchyma. "Serum FGF19 levels were determined by ELISA in acute pancreatitis patients and healthy volunteers." (PMID 25470824, 2014). "In patients with acute pancreatitis, FGF19 levels were lower than in controls." (PMID 25470824, 2014).
adrenocortical carcinoma (1 paper, 2017). "In these seven patients, three PRs (two with FGFR2 fusion-positive iCCA and one with urothelial cancer with FGFR2 and FGF19 amplification) and two durable SDs with tumour reduction (FGFR2 fusion-positive iCCA and adrenocortical carcinoma with FGFR1 amplification) were observed." (PMID 28972963, 2017).
alcohol use disorder (1 paper, 2021). "Serum FGF19 level and FGF19 mRNA expression both increase strongly in patients with alcohol use disorder." (PMID 34490035, 2021).
alcohol-related disorders (1 paper, 2021). Disorders related to or resulting from abuse or mis-use of alcohol. "Recent studies suggest that FGF19, FGF21, and FGF23 are associated with alcohol and alcohol-related disorders." (PMID 34490035, 2021). "Members of fibroblast growth factor (FGF) 19 superfamily, including FGF19, FGF21, and FGF23, are major endocrine mediators that play an important role in alcohol metabolism and alcohol related disorders." (PMID 34490035, 2021).
arteriosclerosis (1 paper, 2020). A vascular disorder characterized by thickening and hardening of the walls of the arteries. "However, few studies revealed the associations of FGF19 with arteriosclerosis indices, such as baPWV and AIP." (PMID 32477430, 2020). "The role of serum fibroblast growth factor 19 (FGF19) in arteriosclerosis is not well known." (PMID 32477430, 2020). "The arteriosclerosis parameters, including baPWV and AIP, significantly decreased across ascending tertiles of serum FGF19 levels (all p for trend < 0.001)." (PMID 32477430, 2020).
Arthritis (1 paper, 2025). Inflammation of a joint. "Additionally, many of the other proteins have been indicated in arthritis or pain conditions such as VEGFR3, FGR, TNFRSF6B, FGF19, DKK3 and proteins belonging to CCL, MMP and CXCL families." (PMID 41170664, 2025).
asthma (1 paper, 2023). "FGF19 had a negative association with asthma among overweight/obese subjects whereas FGF21 had a positive association." (PMID 36973952, 2023).
atrial fibrillation (1 paper, 2023). A disorder characterized by an electrocardiographic finding of a supraventricular arrhythmia characterized by the replacement of consistent P waves by rapid oscillations or fibrillatory waves that vary in size, shape and timing and are accompanied by an irregular ventricular response. "This study aimed to investigate the role of the gut microbiota (GM)–bile acid (BA)–fibroblast growth factor (FGF) 19 axis in patients with atrial fibrillation (AF)." (PMID 37186335, 2023).
Atrophy (1 paper, 2021). Any weakening or degeneration, especially through lack of use. "Therefore, activation of SIRT‐1 might be critical for FGF19 to attenuate PA‐induced muscle atrophy, metabolic disturbance and the decline in FNDC‐5/irisin expression." (PMID 33751819, 2021).
autoimmune disease (1 paper, 2021). A disorder resulting from loss of function or tissue destruction of an organ or multiple organs, arising from humoral or cellular immune responses of the individual to their own tissue constituents. "Fibroblast Growth Factor 19 (FGF19) analogues also showed good results, especially in PBC, while, although PBC and PSC are autoimmune diseases, immunosuppressive drugs had disappointing effects." (PMID 33919600, 2021).
Cachexia (1 paper, 2026). Severe weight loss, wasting of muscle, loss of appetite, and general debility related to a chronic disease. "Given the critical role of FGF19 in metabolic regulation, modulation of FGF19 expression or activity could potentially ameliorate metabolic disturbances and improve the nutritional status of patients with cancer cachexia." (PMID 41328353, 2026). "FGF19 is involved in bile acid metabolism, which is regulated by the gut microbiota; thus, FGF19 may indirectly modulate the composition and function of gut microbiota via its effects on bile acid metabolism, ultimately contributing to the development of cachexia." (PMID 41328353, 2026).
cerebrovascular diseases (1 paper, 2024). "Moreover, FGF-19 appeared to be positively associated with ischemic stroke, further emphasizing its relevance in cerebrovascular diseases." (PMID 38892848, 2024).
Chronic diarrhea (1 paper, 2019). The presence of chronic diarrhea, which is usually taken to mean diarrhea that has persisted for over 4 weeks. "Finally, another method to unravel BAM is FGF19 which is measured by enzyme-linked immunosorbent assay (ELISA) in the serum of patients with chronic diarrhea." (PMID 31726982, 2019).
chronic myeloid leukemia (1 paper, 2017). "Importantly, targeting FGF19/FGFR4 axis by ponatinib, a third-generation inhibitor of chronic myeloid leukemia, overcomes HCC resistance of sorafenib by enhancing ROS-associated apoptosis in sorafenib-treated HCC." (PMID 28069043, 2017).
Cognitive impairment (1 paper, 2023). Abnormal cognition is characterized by deficits in thinking, reasoning, or remembering. "Our results revealed that decreasing FGF19 and FGF21 levels were associated with cognitive impairment in MDD patients, which need further verification." (PMID 37266540, 2023).
corticobasal syndrome (1 paper, 2019). Corticobasal syndrome (CBS) is a rare neurodegenerative disease characterized by multifaceted motor system dysfunctions and cognitive defects such as asymmetric rigidity, bradykinesia, limb apraxia, and visuospatial dysfunction. "Disease-specific analyses revealed lower group levels of FGF-5, FGF-19 and SPOCK1 in multiple system atrophy compared with progressive supranuclear palsy and corticobasal syndrome." (PMID 30867224, 2019).
Crohn's colitis (1 paper, 2012). Crohn's disease affecting the colon. "FGF19 dynamics in patients with Crohn's colitis and disease controls during the first 6 hours after CDCA ingestion and after 8 days of CDCA ingestion." (PMID 23189156, 2012).
dermatofibrosarcoma protuberans (1 paper, 2026). Dermatofibrosarcoma protuberans (DFSP) is a rare infiltrating soft tissue sarcoma, generally of low grade malignancy, arising from the dermis of the skin and characteristically associated with a specific chromosomal translocation t(17;22). "In dermatofibrosarcoma protuberans (DFSP), FGF19 activates downstream signaling pathways by binding to FGFR1 and FGFR2, thereby promoting cell proliferation, survival, and migration, and ultimately driving tumor growth." (PMID 41328353, 2026).
diarrhoea (1 paper, 2022). "Remarkably, FGF19 was found downregulated in cases of chronic diarrhoea caused by bile acid malabsorption, thus this gene could be an indicator of increased risk of diarrhoea in cancer patients taking gefitinib." (PMID 35216325, 2022).
esophageal reflux (1 paper, 2020). "Patients with esophageal reflux may be more likely to suffer an increase in FGF19, and all the factors that induced ER stress may facilitate the upregulation of FGF19 and eventually leads to a vicious circle, since increased FGF19, in turn, will promote tumor progression." (PMID 32111983, 2020).
fibromyalgia (1 paper, 2022). A chronic disorder of unknown etiology characterized by pain, stiffness, and tenderness in the muscles of neck, shoulders, back, hips, arms, and legs. "The top five proteins that distinguished fibromyalgia patients from plasma controls were in serum STAMBP, SIRT2, CD40, AXIN1 and IL-7 and in CSF (CCL19, CCL23, IL-18, CX3CL1, FGF19, CXCL10, CCL11)." (PMID 36327322, 2022).
glioblastoma multiforme (1 paper, 2026). "Mechanistic studies are necessary to investigate how FGF19 interacts with other pathways, such as integrin signaling in glioblastoma multiforme, and its role in tumor progression, with the potential to reveal novel therapeutic targets and inform combination strategies." (PMID 41328353, 2026). "In glioblastoma multiforme (GBM), FGF19 can also significantly enhance the proliferation, migration, and invasiveness of GBM cells." (PMID 41328353, 2026).
glioma (1 paper, 2026). A benign or malignant brain and spinal cord tumor that arises from glial cells (astrocytes, oligodendrocytes, ependymal cells). "In glioma cells, the regulatory role of FGF19 within the Wnt/β-catenin pathway is particularly evident." (PMID 41328353, 2026). "Increased levels of FGF19 are observed with the downregulation of miR-520e, which leads to the stabilization of β-catenin and the activation of the Wnt/β-catenin pathway, driving glioma cell proliferation and invasion." (PMID 41328353, 2026).
heart failure (1 paper, 2025). Inability of the heart to pump blood at an adequate rate to meet tissue metabolic requirements. "In patients with heart failure, the level of the intestinal epithelial secretory factor, FGF19, is elevated, which promotes myocardial hypertrophy, causing heart failure." (PMID 40027477, 2025).
influenza (1 paper, 2025). An acute viral infection of the respiratory tract, occurring in isolated cases, in epidemics, or in pandemics; it is caused by serologically different strains of viruses (influenzaviruses) designated A, B, and C, has a 3-day incubation period, and usually lasts for 3 to 10 days. "Conversely, FGF‐19 concentrations were lower in women who had previously received an influenza vaccine." (PMID 40949320, 2025).
intrahepatic cholestasis (1 paper, 2017). A cholestasis characterized by impairment of the bile flow caused by obstruction located in the liver. "On the other hand, FGF19 mRNA expression in the liver was reported to be increased by both extrahepatic and intrahepatic cholestasis." (PMID 28570655, 2017). "Although FGF19 mRNA is absent in normal liver, FGF19 gene expression was reported to increase in response to both extrahepatic and intrahepatic cholestasis." (PMID 28570655, 2017).
ischemia (1 paper, 2025). A hypoperfusion of the BLOOD through an organ or tissue caused by a PATHOLOGIC CONSTRICTION or obstruction of its BLOOD VESSELS, or an absence of BLOOD CIRCULATION. "In conclusion, the changes in FGF-19 and FGF-21 levels in blood reflect their potential roles among patients after transplantation/ FGF-19 may have a protective effect on the graft during the period of ischemia and subsequent reperfusion, whereas FGF-21 seems to enhances hepatocyte regeneration." (PMID 40648894, 2025).
Left atrial enlargement (1 paper, 2023). Increase in size of the left atrium. "Consistently, the relatively deficient FGF19 and its negative correlation with left atrial enlargement were detected in patients with AF." (PMID 37186335, 2023).
liver dysfunction (1 paper, 2025). "The decrease in FGF19 levels immediately after transplantation suggests the resolution of prior liver dysfunction, while its subsequent gradual increase indicates potential support for regenerative processes." (PMID 39941067, 2025).
malnutrition (1 paper, 2022). Inadequate nutrition resulting from poor diet, malabsorption, or abnormal nutrient distribution. "Limited data from pre-clinical models of malnutrition and malnourished children suggest that the increased levels in bile acids lead to FXR activation and an increase in FGF-19 subsequently leading to suppressed hepatic bile acid synthesis, illustrated by decreased Cyp7a1 expression." (PMID 36402829, 2022).
muscle atrophy (1 paper, 2023). The loss of muscle tissue due to inactivity or disease. "As skeletal muscle atrophy in CKD can result from several interrelated mechanisms leading to an imbalance between protein synthesis and degradation, we further investigated whether the beneficial effects of FGF19 could implicate pathways such as the ubiquitin–proteasome or myostatin." (PMID 37015932, 2023).
nicotine dependence (1 paper, 2023). Physical and psychological dependence on nicotine. "In a previous study on nicotine dependence male subjects, the FGF19 levels in CSF were found positively related to the score of BDI." (PMID 37266540, 2023).
non-small cell lung carcinoma (1 paper, 2023). A group of at least three distinct histological types of lung cancer, including non-small cell squamous cell carcinoma, adenocarcinoma, and large cell carcinoma. "The expression of FGF19 is significantly up-regulated in non-small cell lung cancer, and is associated with poor prognosis." (PMID 36751636, 2023).
Oral Squamous Cell Carcinomas (1 paper, 2021). "In conclusion, the present study demonstrates that melatonin suppresses oral squamous cell carcinomas invasion and migration through blocking FGF19/FGFR4 pathway." (PMID 34576070, 2021).
pancreatic ductal adenocarcinoma (1 paper, 2020). An infiltrating adenocarcinoma that arises from the epithelial cells of the pancreas. "In this study, we examined the expression and roles of FGF19/FGFR4 signaling in human pancreatic ductal adenocarcinoma (PDAC)." (PMID 33066597, 2020).
pancreatitis (1 paper, 2014). Inflammation of the pancreas. "To obtain an impression of FXR activation in patients with AP, we studied plasma FGF19 levels in patients with predicted severe pancreatitis." (PMID 25470824, 2014).
periodontitis (1 paper, 2020). An acute or chronic inflammatory process that affects the tissues that surround and support the teeth. "In periodontitis, the underlying immunoinflammatory dysregulation shows a decrease in the capacity of normalizing glycemia, as shown by an inverse relation to FGF-19 and FGF-21." (PMID 31998807, 2020).
postmenopausal osteoporosis (1 paper, 2020). Metabolic disorder associated with fractures of the femoral neck, vertebrae, and distal forearm. "In this study, we evaluated the changes in serum bile acid and FGF19 levels in Chinese women with postmenopausal osteoporosis, and the relationship between BMD and bile acid metabolism was assessed." (PMID 32187280, 2020). "Therefore, in this study, we aimed to examine the bile acid metabolism of patients with postmenopausal osteoporosis by evaluating the levels of total bile acid and fibroblast growth factor 19 (FGF19)." (PMID 32187280, 2020).
short bowel syndrome (1 paper, 2016). "In this condition short bowel syndrome results in low serum FGF19 levels and dysfunction of the FXR-FGF19 axis, which are considered as primary causes of disproportionate BA synthesis in the liver." (PMID 28008998, 2016).
triple-negative breast carcinoma (1 paper, 2020). An invasive breast carcinoma which is negative for expression of estrogen receptor (ER), progesterone receptor (PR), and human epidermal growth factor receptor 2 (HER2).
ulcerative colitis (1 paper, 2020). An inflammatory bowel disease involving the mucosal surface of the large intestine and rectum. "The aim of the study was to evaluate serum FGF19 level and its correlation with clinical and endoscopic disease activity indices along with inflammatory biomarkers including serum CRP and fecal calprotectin levels in patients with ulcerative colitis (UC)." (PMID 32565779, 2020).
uremia (1 paper, 2023). A clinical syndrome associated with the retention of renal waste products or uremic toxins in the blood. "Before investigating the impact of FGF19 on skeletal muscle of CKD mice, we verified the impact of uremia and FGF19 treatment on the FGF15/19 signaling machinery in soleus muscle." (PMID 37015932, 2023).
vitamin deficiency (1 paper, 2022). A disorder that is caused by the deficiency of a vitamin. "The low C4 and high FGF19 fasting serum levels in these patients with steatorrhea and severe fat-soluble vitamin-deficiency fit predictions from knockout mouse models of OSTα-deficiency." (PMID 36148443, 2022).
vulvar cancer (1 paper, 2022). "After functional annotation, FGF19 and CCND1, involved in the development of the reproductive tract, cell growth and vulvar cancer, were identified as the possible candidate genes of vulvar traits." (PMID 35893031, 2022). "In this refined region, FGF19 and CCND1, involved in the development of the reproductive tract, cell growth and vulvar cancer, could be new candidate genes affecting VL." (PMID 35893031, 2022).
Wolman disease (1 paper, 2023). Wolman disease represents the most severe manifestation of lysosomal acid lipase deficiency. "Through the development of a liver organoid using iPSCs from Wolman patients, researchers have discovered possible therapeutic benefits of OCA and FGF19 in Wolman disease." (PMID 37511351, 2023).